IL1B (interleukin 1 beta)
Diseases named in the same sentence as IL1B in open-access papers (continued):
Sharing a sentence is not in itself a finding about the gene and the disease.
hepatocellular carcinoma (125 papers, 2007 to 2026). A malignant tumor that arises from hepatocytes. "In the present study, we aimed to evaluate the impact of IL‐1β single nucleotide polymorphisms on the hematogenous dissemination and prognosis of hepatocellular carcinoma." (PMID 38798075, 2024). "The IL-1B −511T allele showed evidence of an association with increased cervical cancer risk but demonstrated a protective role in the development of hepatocellular carcinoma." (PMID 23704929, 2013). "Accordingly, IL-1β is linked to a rapid nuclear accumulation of p65 in human hepatoma cells." (PMID 38067111, 2023). "In hepatocellular carcinoma (HCC), M1 macrophage infiltration in HCC tissues is linked to PD-L1 expression in HCC cells, induced by the inflammatory cytokine IL-1β secreted by M1 macrophages." (PMID 39941858, 2025). "Single nucleotide polymorphisms (SNPs) within the promotor region of the IL-1β gene can affect the progression towards liver cirrhosis and hepatocellular carcinoma (HCC)." (PMID 36678401, 2022). "Genetic polymorphisms in IL-1β are associated with gastric cancer, hepatitis C virus and hepatitis B virus linked with hepatocellular carcinoma (HCC)." (PMID 30139338, 2018). "Functional assays demonstrated that DHA-treated cells exhibited increased secretion of TNF, IL1β, ROS, and PD-L1, accompanied by enhanced cytotoxic activity against hepatocellular carcinoma cells in a co-culture system." (PMID 41599687, 2026). "For instance, exosomes released from the HepG2 cell line, a hepatocellular carcinoma model, in response to palmitate fatty acid treatment, promote pro-IL-1β expression and the release of mature IL-1β from THP-1 monocytic cells." (PMID 40141358, 2025). "FOXO6 promotes inflammation by activating cytokine IL-1β and induces lipid triglyceride accumulation in the mouse liver and human hepatocellular carcinomas." (PMID 38835896, 2024). "In another research, Gao and colleagues exhibited that the progression of IL-1β-mediated hepatocellular carcinoma is accelerated through inflammasome accumulation and self-recruitment when autophagy is inhibited in macrophages." (PMID 39315094, 2024). "Our results indicated the specific mechanism by which cholesterol metabolism regulates the ferroptosis in hepatocellular carcinoma cells through IL1B signaling." (PMID 38191842, 2024). "Ferroptosis in hepatocellular carcinoma promotes tumor growth and metastasis through a macrophage/IL1β/neutrophil axis, which can induce sorafenib resistance, with targeting this inflammatory pathway enhancing sorafenib efficacy." (PMID 39315094, 2024). "The present result for IL1B SNP rs1143633 replicates for the finding from hepatocellular carcinoma study in Asians-Korean9." (PMID 37147350, 2023). "Similar observations were found in adipocytes co-cultured with exosomes derived from hepatocellular carcinoma, where the induction of pro-inflammatory cytokines IL-6, IL-8, IL-1β and CCL2 promoted tumor growth and angiogenesis." (PMID 37833751, 2023). "Lower levels of caspase-1, IL-1β, and IL-18 were observed in hepatocellular carcinoma (HCC) tissues compared with adjacent normal ones, implying the role of pyroptosis in tumorigenicity." (PMID 35432318, 2022). "In a hepatoma mouse model, combination treatment of anti-PD-1 antibodies with anti-IL-1β antibodies or the PIM inhibitor AZD1208 led to complete tumor regression." (PMID 36429128, 2022). "Our results showed that higher circulating inflammatory cytokine IL-17 and lower IL-1β levels were beneficial for the HBV spontaneous clearance; and higher IL-17 levels were negatively associated with the probability of hepatoma development." (PMID 35785033, 2022). "As previously reported, AgNPs induced inflammasome and significantly high levels of IL-1β production in Hep G2 cells, a human hepatoma cell line." (PMID 34685095, 2021).
hepatocellular carcinoma (continued). "Our study establishes that the NLRP3 inflammasome complex, which can induce proinflammatory cytokine IL-1β production, is assembled and activated in human hepatoma cells." (PMID 34431717, 2021). "In vitro, ADAM8 expression was upregulated in hepatoma, endothelial, and stellate cell lines by various mediators of steatohepatitis including fatty acid (linoleic-oleic acid), IL-1β, TNF-α, IFN-γ, and TGF-β." (PMID 33814981, 2021). "In this study, we found that IL-1β from activated HSCs promoted the proliferation and invasiveness of hepatoma cells." (PMID 30794626, 2019). "In the current study, we show that the CRP promoter is up-regulated by IL-6/ IL-1β or with IL-6 alone in a human hepatoma cell line." (PMID 29644527, 2018). "There is recent evidence that LRG1 is induced by IL-6 and synergistically up-regulated with either IL-1β or tumor necrosis factor-α in a pattern similar to that exhibited by type 1 acute-phase proteins in human hepatoma HepG2 cells." (PMID 29513714, 2018). "For example, SelP expression is downregulated by TNFα stimulation of 3T3-L1 cells, by IL-6 in human hepatoma cells, and studies of the human SelP promoter have shown it is responsive to IL-1β, IFNγ and TNFα in HepG2 cells." (PMID 30571741, 2018). "In human hepatoma cells, gemcabene inhibited IL-6 plus IL-1β-induced CRP production in a concentration-dependent manner, reaching 70% inhibition at 2 mM." (PMID 29644527, 2018). "Synergism between IL-1β/TNFα and IFNβ for iNOS expression was actually even more pronounced in alternate murine Hepa56.1D hepatoma cells." (PMID 28824623, 2017). "CCL3, CCL3L1, JUN, IL8, and IL1B were identified in inflammation mediated by chemokine and cytokine signaling pathway (P00031) in the hepatic carcinoma samples with metastasis, and subsequently confirmed by quantitative real-time polymerase chain reaction." (PMID 28427195, 2017). "In hepatocellular carcinoma cells, hypoxia induces caspase-1 activation, cleavage and release of proinflammatory cytokines, IL-1β and IL-18." (PMID 29184853, 2017). "On a cellular level, we demonstrate that IFNβ potently synergizes with the prototypic inflammatory cytokines IL-1β/TNFα for induction of iNOS in primary murine hepatocytes and murine Hepa56.1D as well as Hepa1-6 hepatoma cells." (PMID 28824623, 2017). "In conclusions, CCL3, CCL3L1, JUN, IL8, and IL1B have the potential to be considered as candidates for future molecular diagnosis of the hepatic carcinoma with metastasis." (PMID 28427195, 2017). "And the number of identified DEGs and the level of IL1B presented the potential to be used to supervise the progression of hepatic carcinoma." (PMID 28427195, 2017). "6-Gingerol protects the HuH7 human hepatoma cells against IL-1β-induced inflammatory insults through inhibition of the reactive-oxygen-species-activated NF-κB/cyclooxygenase-2 pathway." (PMID 25658238, 2015). "To further assess the roles of TNF-α and IL-1β in the pathogenesis of RA-anemia and their effects on IL-6-induced hepcidin mRNA expression, we performed in vitro real-time RT-PCR assays using a hepatoma-derived cell line." (PMID 24286116, 2013). "LGR is induced by interleukin-6, interleukin-1-beta and transforming growth factor-alpha in hepatoma cells, and is over-expressed in livers of the mice challenged by lipopolysaccharide, rendering it an acute phase protein." (PMID 24066001, 2013). "In human hepatoma cells, IL-1β also stimulates DNA binding and the protein accumulation of HIF-1α, indicating the close relationship between IL-1β and HIF-1α activity." (PMID 23166763, 2012). "It has been reported that the expression of LRAG in human hepatoma cells was induced by IL-6, IL-1β, and TNFα; and that the LRAG expression was enhanced by the induction of acute inflammation in mice." (PMID 22568928, 2012).
hepatocellular carcinoma (continued). "Alternatively, Gharavi and El-Kadi (2005) showed in murine hepatoma cell lines that Cyp1a1 is down-regulated by the proinflammatory cytokines interleukin 1β (Il-1β), IL-6, and tumor necrosis factor α in an AHR-dependent manner." (PMID 19165387, 2009). "In vitro studies in hepatoma cell lines illustrate the downregulation of Cyp3a11 exposed to the proinflammatory cytokines IL-6, IL-1β and TNF-α." (PMID 18059400, 2008). "On the other hand, IL-1β (such as otherproinflammatory cytokines) is a potent inducer of NF-κB and it has beenshown that extract of Thymus pulegioides can inhibit activation of NF-κBby IL-1β in human hepatoma cells." (PMID 18288268, 2007). "To investigate whether pro-inflammatory stimuli regulate ACBP/DBI expression, we stimulated HepG2, a human hepatoma cell line, and peripheral blood mononuclear cells (PBMCs) from healthy human donors with lipopolysaccharide (LPS), IL-1β, and TNFα." (PMID 40867617, 2025). "IL-1β secreted by M1 macrophages can mediate the immune escape of tumor cells and thus play a pro-carcinogenic role by inducing the expression of the programmed cell death ligand PD-L1 in hepatocellular carcinoma." (PMID 38762529, 2024). "Finally, one chemical, indomethacin, and one protein, IL1B, were identified as the essential node for cholesterol-mediated ferroptosis in hepatocellular carcinoma cell." (PMID 38191842, 2024). "Furthermore, based on the predicted results with STITCH, we identified indomethacin and IL1B as the essential node for cholesterol-mediated ferroptosis in hepatocellular carcinoma cell." (PMID 38191842, 2024). "Additionally, IL‐1β has been reported to upregulate PD‐L1 expression in hepatocellular carcinoma cells, while how the IL‐1β and the elevated PD‐L1 modulated the TIME remains elusive." (PMID 37009412, 2023). "IL-1β significantly reduced HBV replication levels in hepatoma cells." (PMID 37208599, 2023). "For stimulation of hepatoma cells, a combination of fatty acid and IL-1β was used." (PMID 33814981, 2021). "Thus, we alternatively stimulated HepG2 cells (human hepatoma cell line) with Pg-derived LPS or human recombinant IL-1β as positive control and examined mRNA expressions of CCL2, CXCL10, and FOXO1 using real time PCR." (PMID 34526589, 2021). "Furthermore, after ROSs and NLRP3 inflammatory corpuscles were activated, the secretion of IL-1β was promoted, and the rates of proliferation, migration, and invasion of hepatoma cells were accelerated." (PMID 35095920, 2021). "In liver cells or hepatoma cell lines (e.g., Huh-7 cells), TNFα and IL-1β induced by LPS only have minor effects on SOCS expression and their effects on GH resistance are mediated by reducing GHR gene transcription, probably through inhibition of Sp1/3 binding to GHR promoter." (PMID 32082258, 2020). "Moreover, recombinant IL-1β and M1 macrophage-derived IL-1β induce PD-L1 expression at the cell surface of human and murine hepatocellular carcinoma cells." (PMID 33261061, 2020). "These compounds decreased the gene expression of tumor necrosis factor-alpha (TNF-α), interleukin-6 (IL-6) and interleukin-1beta (IL-1β) in lipopolysaccharide (LPS) induced inflammation in a hepatocellular carcinoma cell line (HepG2) in a dose-dependent manner." (PMID 31484451, 2019). "Previously, we discovered IL-1β-producing M2 polarised TAMs in hepatocellular carcinoma; therefore, we investigated whether a similar phenomenon could be seen in PDAC." (PMID 31588122, 2019). "As determined in this latter cellular model, IFNβ directs STAT1 binding to a critical regulatory site within the murine iNOS promoter (−912 to −1,029 bp relative to the TSS), a process that, in Hepa1-6 hepatoma cells, demanded simultaneous pro-inflammatory signaling by IL-1β/TNFα." (PMID 28824623, 2017). "It indicated that IL-8 might be mainly induced by IL-1β through the JNK pathway to participate in the process of hepatic carcinoma cells metastasis." (PMID 28427195, 2017).
hepatocellular carcinoma (continued). "Besides, in this study, we also found the up-regulated JUN and IL1B in the samples of hepatic carcinoma with metastases." (PMID 28427195, 2017). "Likewise, our in vitro studies on human hepatoma cell lines and 3D spheroid cultures indicate that IL-1β released by activated macrophages may contribute to tumor growth and impact the antitumoral activity of sorafenib." (PMID 38672578, 2024). "In 2020, Chen and colleagues elucidated a mechanism by which IRAK1 promotes metastasis in hepatocellular carcinoma (HCC) through the activation of the NLRP3/MAPKs/IL-1β pathway." (PMID 39451208, 2024). "The study shows that NLRP3 is upregulated in oxaliplatin‐resistant HCC cells and has a tumor‐intrinsic function in generating an immunosuppressive hepatocellular carcinoma environment by activating IL‐1β and PD‐L1 upregulation." (PMID 38116060, 2023). "HIV patients exhibit a faster rate of fibrosis advancement, and the surged levels of IL-1β in chronic HCV infection appears to augment the onset of hepatocellular carcinoma (HCC)." (PMID 36405584, 2022). "Furthermore, in vitro experiments in primary mouse hepatocytes and human hepatoma cell lines HuH7 and HepG2 together with in vivo experiments demonstrated that IL-1β exposure was sufficient to suppress transcription of Nr1h4, Abcb11, Abcc2, and Abcg5/8, findings that characterize the PNAC liver." (PMID 29643332, 2018). "Finally, in order to further validate these 5 DEGs, RT-qPCR were performed and the result was the same with that of RNA-seq, demonstrating that CCL3, CCL3L1, JUN, IL8, and IL1B were reliable and available to be used as the candidates for hepatic carcinoma with metastasis." (PMID 28427195, 2017). "Studies show that miR-98 can inhibit the Wnt/β-catenin signaling pathway in hepatocellular carcinoma and retinoblastoma, possibly explaining miR-98-5p's role in reducing ECM degradation in IL-1β-stimulated CHON-001 cells." (PMID 38615043, 2024). "To explore the role of ANGPTL3 in IL-1β-induced NF-κB activation, we overexpressed ANGPTL3-Flag plasmids in the human embryonic kidney cell line HEK293T and the human hepatocellular carcinoma cell line Hep3B." (PMID 37634084, 2024). "In hepatocellular carcinoma, sorcin is considerably upregulated and caspase-1, GSDMD-N and IL-1β are significantly decreased." (PMID 39616223, 2024). "IL-1β produced by inflammatory macrophages increases PD-L1, as well as HIF-1α-dependent CSF-1 expression in hepatoma cells, facilitating TAM accumulation." (PMID 36845555, 2023). "In summary, our study reveals that the SREBP2 inhibitor betulin sensitizes hepatocellular carcinoma to lenvatinib by inhibiting the mTOR/IL-1β pathway, which may be a promising therapeutic strategy for patients with HCC." (PMID 37434430, 2023). "MiR‐98 mimics notably elevate the levels of IL‐1β and TNF‐α in TAM under hepatocellular carcinoma conditions, but significantly lower IL‐10 and TGF‐β, meaning that M2 turns into M1, thus repressing EMT, invasion, and migration of SMMC7721 and HepG2 cells." (PMID 38098217, 2023). "Considering HBV progression, the levels of IL-1β, IL-17, IL-10, IP-10, MCP-1, and MIP-1β were all markedly decreased in the hepatoma group compared to that in the CHB group." (PMID 35785033, 2022). "Previous studies have demonstrated that IL-1β can induce EMT or endothelial-to-mesenchymal in a variety of epithelial or endothelial cells, such as hepatocellular carcinoma cells, esophageal squamous cell carcinoma cells, aortic endothelial cells, and so on." (PMID 34344357, 2021). "The anti-inflammatory effect in the sciatic nerve chronic constriction injury (CCI)-induced neuropathic pain model and anticancer effect in the hepatocellular carcinoma (HCC) animal model are reported to be caused by RosA, which regulates the expression of TNF-α, COX-2, IL-1β, and p65." (PMID 32823673, 2020).
hepatocellular carcinoma (continued). "Resaerchers have reported that luteoloside suppresses hepatocellular carcinoma cells (HCC) through the inhibition of HCC migration and invasion and has the capacity to downregulate the expression level of NLRP3, caspase-1 and IL-1β, suppressing proliferation and metastasis of HCC." (PMID 32650482, 2020). "Overexpression of TUC339 in hepatocellular carcinoma (HCC) cells suppressed the expression of proinflammatory factors, such as IL-1β and TNF-α, and knockdown of TUC339 obtained an opposite effect." (PMID 32190702, 2020). "In human neurons, GLS1 expression was upregulated by IL-1β or TNF-α treatment, and in a rat hepatoma model IL-6 or TNF-α treatment indirectly upregulated c-MYC expression." (PMID 28399896, 2017). "This is consistent with higher proinflammatory cytokines (IL-1β, IL-6 and TNF) in hepatoma compared with healthy tissues." (PMID 27551463, 2015). "Although, it is induced by IL-6, IL-1-β and TNF-α in hepatoma cells, and overexpressed in the liver of mice challenged by lipopolysaccharide rendering it as an acute phase protein, its real physiological functions has not been clarified so far." (PMID 24497876, 2014). "Furthermore, TNFα and IL1β treatment of Hep3B human hepatoma cells and mice resulted in decreased expression of RXRα, PPARα, PPARγ, LXRα, as well as their co-activators PGC1α and PGC-1β, which may contribute to the cytokine induced modulations in hepatic energy homeostasis." (PMID 24112857, 2013). "IL-1β can also attenuate interferon-induced antiviral activity and STAT1 activation in the liver, and modulate immune responses in hepatitis virus-related hepatocellular carcinoma." (PMID 23704929, 2013). "Others have demonstrated that IL-1β also promotes CD55 expression in articular chondrocytes, hepatoma cells, and intestinal epithelial cells." (PMID 22590509, 2012). "In hepatocellular carcinoma (HCC), LPS promotes cell survival, proliferation, invasion, and production of pro-inflammatory mediators, including TNF-α, iNOS, IL-1β, IL-6, CCL-2, CCL-22, vimentin, and epidermal growth factor receptor (EGFR), through the induction of TLR4 signaling." (PMID 40444051, 2025). "Moreover, a recent study reported a synergistic effect of IFN-γ and IL-1β on PD-L1 expression in hepatocellular carcinoma, mediated by the increase in IRF-1 and the IFN-γ receptor expression induced by IL-1β." (PMID 37834467, 2023). "This was demonstrated using the diethylnitrosamine (DEN) mouse model of hepatocellular carcinoma (HCC), in which the mitophagy effector FUNDC1 was specifically deleted in hepatocytes leading to aberrant activation of the Nlrp3 inflammasome and IL-1β-driven hepatocyte hyperproliferation." (PMID 35517498, 2022). "For example, sorafenib could motivate the cytotoxicity of natural killer cells (NKs) to hepatocellular carcinoma (HCC) cells by inducing the pyroptotic cell death in macrophages, and this effect was significantly related to the secretion of IL-18 and IL-1β." (PMID 35873495, 2022). "Indeed, several in vitro studies described IL-1β, IL-17, TNFα, IL-4, IL-33 and IL-10 as additional LRG1 regulators in hepatoma cells, endothelial cells, bronchial epithelial cells and “alternatively activated” (M2) macrophages." (PMID 35062948, 2022). "Additionally, CARD oil decreased the levels of TNF-α, IL-1β and NF-κB in the DENA-induced hepatocellular carcinoma." (PMID 36354677, 2022). "Data indicate that NF-κB activation by IL-1β/TNFα, likely mediated by an active proximal NF-κB site at −85 to −76 bp relative to the TSS, supports STAT1 binding to the iNOS promoter in murine Hepa1-6 hepatoma cells." (PMID 28824623, 2017). "Although RIG-I-deficient hepatoma cells have been shown to produce low levels of IL-1β during HCV infection, we found that HCV infection of immune-competent hepatoma cells and primary hepatocytes does not trigger appreciable production of IL-1β." (PMID 23633957, 2013).